PQBP1 (polyglutamine binding protein 1)
Diseases named in the same sentence as PQBP1 in open-access papers (continued):
Sharing a sentence is not in itself a finding about the gene and the disease.
spinocerebellar ataxia type 1 (2 papers, 2021 to 2024). Spinocerebellar ataxia type 1 (SCA1) is a subtype of type I autosomal dominant cerebellar ataxia (ADCA type I) characterized by dysarthria, writing difficulties, limb ataxia, and commonly nystagmus and saccadic abnormalities. "Similarly, PQBP1 was found to bind to mutated ataxin-1, known to be in association with spinocerebellar ataxia type 1 (SCA1)." (PMID 39205314, 2024).
viral infection (2 papers, 2019 to 2024). "In absence of PQBP1, the innate reaction was distinctly reduced upon lentiviral infection, whereas the immune response towards a dsDNA-virus infection by MHV-68 or transfected DNA (B-DNA and HT-DNA) was not affected by depletion of PQBP1, suggesting a specific response to retroviral PAMPs." (PMID 39205314, 2024).
Anxiety (1 paper, 2013). Intense feelings of nervousness, tension, or panic often arise in response to interpersonal stresses. "In PQBP1-knockdown mice in which the PQBP1 protein levels are reduced to 50% in the adult brain, we observed that anxiety-related cognition is impaired." (PMID 23874697, 2013).
atherosclerosis (1 paper, 2025). A disease characterized by the build-up of fatty material and calcium deposition in the arterial wall resulting in partial or complete occlusion of the arterial lumen. "A WGCNA approach was implemented to identify biologically meaningful gene modules highly correlated with the four key atherosclerosis‐associated RGN driver genes (i.e., AIP, DRAP1, POLR2I, and PQBP1)." (PMID 40112173, 2025).
breast carcinoma (1 paper, 2024). "Pan‐cancer analysis using Clinical Proteomic Tumor Analysis Consortium (CPTAC) database revealed that PQBP1 is overexpressed in various cancer types including breast cancer, colon cancer, and glioblastoma." (PMID 38342602, 2024).
cognitive decline (1 paper, 2018). "PQBP1 and SRRM2 were downregulated in cortical neurons of human AD patients and mouse AD models, and the AAV-PQBP1 vector recovered RNA splicing, the synapse phenotype, and the cognitive decline in the two mouse models." (PMID 30283027, 2018).
glioma (1 paper, 2015). A benign or malignant brain and spinal cord tumor that arises from glial cells (astrocytes, oligodendrocytes, ependymal cells). "Among these 4 proteins, SNX1 and IGHG1 were up-regulated in gliomas, while, PQBP1 and EYA1 were down-regulated in gliomas." (PMID 26370624, 2015). "However, there were no common proteins which were differentially expressed in Grade II and IV with the exception of 4 proteins, SNX1, EYA1, PQBP1, and IGHG1, which were dysregulated across all the grades of gliomas." (PMID 26370624, 2015).
microgliomas (1 paper, 2022). "In microgliomas, polyglutamine binding protein 1 (PQBP1) activates cGAS-STING by interacting with sensing extrinsic tau 3R/4R proteins." (PMID 36741390, 2022).
ovarian carcinoma (1 paper, 2024). A malignant neoplasm originating from the surface ovarian epithelium. "Collectively, these results indicate that high PQBP1 expression is associated with poor prognosis in ovarian cancer patients." (PMID 38342602, 2024). "Here, we show that ≈11% of ovarian cancer patients harbor genetic alteration of PQBP1 and that high levels of PQBP1 are associated with worse outcome." (PMID 38342602, 2024). "The UALCAN database further showed higher protein levels of PQBP1 in cancer tissues, and its expression was related to clinical stage in ovarian cancer, and pan‐cancer analysis showed that PQBP1 is overexpressed in various cancer types." (PMID 38342602, 2024). "We also verified that PQBP1 promotes ovarian cancer progression by regulating the aberrant splicing and degradation of BAX." (PMID 38342602, 2024). "In the present work, we demonstrated that PQBP1 was frequently increased and indicated a poor prognosis in ovarian cancer." (PMID 38342602, 2024). "We then measured apoptosis using Annexin V‐PE/7‐AAD staining and flow cytometry and found that knockdown of PQBP1 expression was sufficient to induce spontaneous apoptosis of ovarian cancer cells." (PMID 38342602, 2024). "To identify the direct targets that account for the function of PQBP1 in ovarian cancer, we compared PQBP1‐bound genes and differential AS events and identified 567 common genes." (PMID 38342602, 2024). "Subsequent investigations revealed that ectopic expression of PQBP1 promoted the development of ovarian cancer in vitro and in vivo." (PMID 38342602, 2024). "In conclusion, our work systematically studied PQBP1‐mediated AS and assessed the role of PQBP1 in ovarian cancer progression." (PMID 38342602, 2024). "Together, the results demonstrate an oncogenic role of PQBP1 in ovarian cancer and suggest that targeting the aberrant splicing mediated by PQBP1 has therapeutic potential in cancer treatment." (PMID 38342602, 2024). "In contrast, PQBP1 depletion led to ROS accumulation, mitochondrial dysfunction, and finally induced apoptosis of ovarian cancer cells." (PMID 38342602, 2024). "Here, it is shown that PQBP1 overexpression promotes tumor progression and indicates worse prognosis in ovarian cancer." (PMID 38342602, 2024). "Our study thus suggests that PQBP1 acts as an oncogenic splicing factor that promotes the survival of ovarian cancer cells." (PMID 38342602, 2024). "Thus, our study provides new insights into the oncogenic splicing factor PQBP1 in ovarian cancer development and suggests that PQBP1 represents a potential target for therapeutic interventions against ovarian cancer." (PMID 38342602, 2024). "Our findings provide strong evidence supporting the role of PQBP1 in ovarian cancer development." (PMID 38342602, 2024). "We further assessed the role of PQBP1 in ovarian cancer tumorigenesis in vivo." (PMID 38342602, 2024). "We further demonstrate that PQBP1 promotes ovarian cancer proliferation and xenograft tumor growth." (PMID 38342602, 2024). "In contrast, the overexpression of PQBP1 inhibited H2O2‐induced apoptosis of ovarian cancer cells." (PMID 38342602, 2024). "Here, the authors report that PQBP1 promotes exon skipping and degradation of BAX, which inhibits apoptosis in ovarian cancer cells." (PMID 38342602, 2024). "Importantly, we show that PQBP1 regulates the AS and expression of BAX and that PQBP1 depletion leads to exon 2 inclusion that in turn upregulates BAX and triggers apoptosis in ovarian cancer cells." (PMID 38342602, 2024). "Taken together, these results indicate that PQBP1‐mediated AS and expression of BAX might play a role in ovarian cancer progression." (PMID 38342602, 2024). "Previous studies have reported that PQBP1 regulates AS of BCL‐X in human A549 cells and Ncam‐1 in mouse neurons, and our present work provides strong evidence that PQBP1 regulates AS of apoptotic genes, including BAX, in ovarian cancer cells." (PMID 38342602, 2024).
prostate carcinoma (1 paper, 2006). A carcinoma that arises from epithelial cells of the prostate gland. "Polyglutamine binding protein 1 and putative prostate cancer tumor suppressor also have two probesets detecting the same transcript, but in these cases one of the probesets generates higher values on the A chip and the other generates higher values on the Plus chip." (PMID 16776839, 2006).
Williams syndrome (1 paper, 2016). "It would be interesting to study other ID etiologies in the future (such as ARX, PQBP1 or Williams syndrome) to check if a specific eye-tracking pattern exists for each of them." (PMID 26918704, 2016).
X-linked intellectual disability (1 paper, 2021). An X-linked intellectual deficiency in which not enough information is known, reported or published to indicate whether a gene causes non-syndromic or syndromic presentations. "Next, we switched to some earlier structural work on the polyglutamine tract-binding protein 1 (PQBP-1) mutants of our laboratory and discussed the implications of their dimerisation in X-linked intellectual disability (XLID)." (PMID 33668121, 2021).
neurodegenerative disease (9 papers, 2013 to 2024). A disorder of the central nervous system characterized by gradual and progressive loss of neural tissue and neurologic function. "PQBP1 has been implicated in both neurodegenerative diseases and developmental disorders.PQBP1 has been shown to interact with the two polyQ disease proteins, ataxin-1 and huntingtin." (PMID 23874697, 2013). "PQBP1 has been studied extensively to be involved in neurodegenerative diseases and innate immunity." (PMID 38342602, 2024). "Tau protein, which is known to be involved in the pathogenesis of various neurodegenerative diseases, including AD and tauopathy, was found to activate microglia via the PQBP1-cGAS-STING pathway to promote brain inflammation, such as TNF, IL-6 and type 1 IFN." (PMID 37201645, 2023). "This demonstrates the potential of targeting PQBP1 as a new common therapy for neurodegenerative diseases." (PMID 35682906, 2022). "Interestingly, PQBP1 was originally identified as a binding protein to polyglutamine (polyQ) tract amino acid sequence that is expanded in a group of neurodegenerative diseases called polyQ diseases." (PMID 34782623, 2021). "The results of this study indicated that microglia-specific depletion of PQBP1 could be used to develop therapeutics against tau-mediated neurodegenerative diseases." (PMID 34782623, 2021). "As previously demonstrated for PQBP1 in the contexts of SCA1, HD, and AD, PQBP3/NOL7 could function as an additional hub molecule in common pathologies across multiple neurodegenerative diseases." (PMID 39103492, 2024).
infection (7 papers, 2018 to 2025). The state of being infected such as from the introduction of a foreign agent such as serum, vaccine, antigenic substance or organism. "The NTD of PQBP1, comprising residues 1 to 46, forms the site of association with an incoming HIV-1 capsid (CA) upon infection of a cell." (PMID 39205314, 2024). "PQBP1 mRNA expression was significantly decreased upon infection with ARV." (PMID 39205314, 2024). "In our experimental setup, PQBP1 did not seem to be involved in cGAS-mediated sensing, suggesting that its involvement could depend on the context of infection." (PMID 38530034, 2024).
cancer (2 papers, 2023 to 2024). A tumor composed of atypical neoplastic, often pleomorphic cells that invade other tissues. "In cancer patients, overexpression of PQBP1 acts as a repressor of IFN-β promoter transcription produced by IFI16 and cGAS induction, resulting in blocked DNA signaling and reduced survival." (PMID 37201645, 2023). "PQBP1 promotes BAX exon 2 skipping to generate a truncated isoform that undergoes degradation by nonsense‐mediated mRNA decay, thus making cancer cells resistant to apoptosis." (PMID 38342602, 2024). "However, the roles of PQBP1 in cancer progression remain largely unknown." (PMID 38342602, 2024).
tumor (2 papers, 2006 to 2024). "In addition, the increased PQBP1 expression was correlated with higher tumor mutational burden in TCGA OV cohort." (PMID 38342602, 2024). "HEY cells with PQBP1 overexpression and control cells (n = 6) were injected subcutaneously into the flanks of nude mice, and tumor growth was measured over time." (PMID 38342602, 2024). "In contrast, knockdown of PQBP1 resulted in reduced tumor mass, tumor volume, and Ki‐67 proliferative index." (PMID 38342602, 2024). "Consistent with this, overexpression of BAX‐L significantly suppressed PQBP1‐induced xenograft tumor growth." (PMID 38342602, 2024). "Overexpression of PQBP1 in HEY cells led to a significant increase in tumor mass and tumor volume." (PMID 38342602, 2024). "In contrast, PQBP1 depletion or splice‐switching antisense oligonucleotides promote exon 2 inclusion and thus increase BAX expression, leading to inhibition of tumor growth." (PMID 38342602, 2024).
PQBP1 also shares sentences with these, for which no sentence is quoted: Alzheimer disease (2 papers); Au-Kline syndrome (2); brain inflammation (2); Kennedy disease (2); neurological diseases (2); schizophrenia (2); amyotrophic lateral sclerosis (1); anal atresia (1); autism (1); ciliopathies (1); colon cancer (1); dementia (1); developmental delay (1); glioblastoma (1); hamel cerebro-palato-cardiac syndrome (1); melanoma (1); motor neuron disease (1); myotonic dystrophy (1); osteosarcoma (1); ovarian tumor (1); Periventricular heterotopia (1); serous ovarian carcinoma (1); spinocerebellar ataxia (1); spinocerebellar ataxia type-16 (1); spondyloepimetaphyseal dysplasia (1); syndromic intellectual disability (1); systemic lupus erythematosus (1); testicular cancer (1).